NOX4 (NADPH oxidase 4)
Diseases named in the same sentence as NOX4 in open-access papers (continued):
Sharing a sentence is not in itself a finding about the gene and the disease.
papillary thyroid carcinoma (8 papers, 2018 to 2026). "The comparative analysis of the expression of the reactive oxygen species-generating NADPH oxidase NOX4 from TCGA data shows that the NOX4 transcript is upregulated in papillary thyroid carcinomas (PTC)-BRAFV600E tumors compared to PTC-BRAFwt tumors." (PMID 37504283, 2023). "An upregulation of NOX4 has already been described in Hashimoto’s thyroiditis and in thyroid cancers with a particularly high expression in papillary thyroid cancers." (PMID 35008579, 2021). "At the current state of data, we provide the first evidence that NOX4 functions as a glycolytic regulator coupling the metabolism to the papillary thyroid carcinoma proliferation." (PMID 30367082, 2018). "Significantly, loss of NOX4 in human papillary thyroid cancer cells decreases HIF1α targeting genes such as SLC2A1 and CA9, highlighting the potential importance of NOX4-mediated metabolic reprogramming in thyroid tumor." (PMID 30367082, 2018). "Since mROS is known to be both necessary and sufficient for HIF stabilization under hypoxia, we report that NOX4 and p22phox in papillary thyroid carcinoma are necessary for mROS production during hypoxia." (PMID 30367082, 2018). "Our results support this observation by showing that, as in papillary thyroid carcinoma (PTC), NOX4, HIF-1α, GLUT-1, and VEGF-A are increased in Th1 cytokines-treated human thyroid cells and in Hashimoto’s thyroid samples." (PMID 33916948, 2021).
aortic aneurysm (7 papers, 2019 to 2025). A ruptured aneurysm located in the wall of the proximal portion of the descending aorta proceeding from the arch of the aorta. "In Marfan mice, NOX4 deficiency results in delayed aortic aneurysm progression and normalization of endothelial dysfunction in Marfan aorta." (PMID 39070552, 2024). "Since dysregulation of the Hif-1α/Vegfa and Tgfb1/Ctgf pathways has been linked to aortic aneurysm progression, these Nox4 target genes likely contribute to aortic pathology in PKG1RQ/+ mice." (PMID 31387997, 2019). "The findings that NOX4 is highly increased in the human and murine MFS aorta, and NOX4-deficient MFS mice experience mitigated aortic aneurysm formation and diminished elastin degradation, demonstrate that NOX4 and/or ROS may be involved in the pathogenesis of aortic changes." (PMID 34572356, 2021). "NOX4 partly contributes to the development of Ang II-induced aortic aneurysms and atherosclerosis by modulating osteopontin expression." (PMID 39070552, 2024). "Tyrosine nitration and reactive oxygen species levels with NOX4 expression increased in the tunica media of aortic aneurysms and cultured vascular smooth muscle cells from Marfan syndrome patients." (PMID 34440716, 2021). "In another study, endothelial dysfunction was prevented in Nox4-deficient MFS mice, which involved, for the first time, NADPH oxidases in the progression of the MFS aortic aneurysm." (PMID 33086603, 2020). "NOX4 upregulation leads to increased Hif-1α and Vegfa expression, and dysregulated HIF-1α /VEGF signaling has been observed in TAAD and linked to aortic aneurysm progression." (PMID 31387997, 2019). "It has been shown that allopurinol treatment reduces oxidative stress by decreasing the expression level of Nox4, in addition to XO, and might block aortic aneurysm in a mouse model of Marfan syndrome." (PMID 40179080, 2025). "In a newly generated MFS mouse model lacking Nox4 gene expression, the integrity of elastic fibers was preserved and aortic aneurysm progression was significantly reduced." (PMID 33086603, 2020).
bladder cancer (7 papers, 2011 to 2025). "This study aims to explore the expression patterns of SH3YL1 in bladder cancer, with a particular focus on its correlation with NOX4, a gene associated with oxidative stress and implicated in cancer progression." (PMID 40362200, 2025). "To evaluate the potential of SH3YL1 and NOX4 as diagnostic biomarkers for bladder cancer subtypes, we conducted ROC (Receiver Operating Characteristic) curve analysis on SH3YL1, NOX4, and the combined SH3YL1 + NOX4 expression levels in NMIBC and MIBC groups." (PMID 40362200, 2025). "The lower predictive values in NMIBC also highlight the specificity of SH3YL1 and NOX4 as potential markers for more invasive forms of bladder cancer." (PMID 40362200, 2025). "In human bladder cancer (urothelial carcinoma), was showed that elevated levels of ROS induced by Nox4 enzyme (a H2O2-generator enzyme) are required for tumor initiation and progression." (PMID 40061896, 2025). "Although Nox4 also plays an essential role in bladder cancer development, the regulatory axis of Nox4 in bladder cancer has not been well studied." (PMID 35293283, 2022). "Overall, MI showed a potent anti-tumor effect against bladder cancer partially via modulating the miR-26b/Nox4 axis." (PMID 35293283, 2022). "Silencing the NOX4 gene in bladder cancer cells reduces intracellular ROS in vitro and blocks cell growth in vivo." (PMID 34073079, 2021). "We performed immunohistochemistry for NOX4 in surgical specimens of human bladder cancer and normal tissue derived from autopsy samples." (PMID 22032647, 2011). "NOX4 expression in urothelial carcinoma cells was observed by immunohistochemical analysis using surgical specimens of human bladder cancer." (PMID 22032647, 2011). "In contrast, NOX4 appears to exert a more nuanced role, exhibiting subtype-specific influences that may reflect its involvement in the molecular heterogeneity of bladder cancer." (PMID 40362200, 2025). "This specificity in MIBC underscores the potential of SH3YL1 and NOX4 to identify patients who may benefit from intensified therapeutic interventions, paving the way for more personalized bladder cancer management strategies." (PMID 40362200, 2025). "This lack of variation led us to examine SH3YL1’s role in bladder cancer progression, focusing on its associations with key oxidative stress-related genes such as NOX4 across bladder cancer subtypes." (PMID 40362200, 2025). "Recently, Nox4 has been revealed to play an important role in the invasion of bladder cancer cells." (PMID 35293283, 2022). "MI efficiently inhibits bladder cancer progression both in vitro and in vivo by inhibiting the Nox4/NF-κB/HIF-1α signaling pathway by directly upregulating miR-26b expression, suggesting that MI might be a potential anticancer agent for bladder cancer." (PMID 35293283, 2022). "NOX4 should therefore be the target molecule in bladder cancer treatment." (PMID 22032647, 2011). "We examined the role of NOX4 in bladder cancer development in vivo." (PMID 22032647, 2011). "Since the expression of NOX4 was relatively high not only in urothelial carcinoma cells but also in dysplasia as precancerous lesions, we hope to develop prophylaxis against bladder cancer occurrence and recurrence with a new strategy focusing on the NOX4-ROS signal." (PMID 22032647, 2011). "From the immunoprofile of NOX4 in normal, dysplastic, and malignant urothelial cells, NOX4 might be involved in an early stage of urothelial carcinogenesis and be a potential new molecular target for bladder cancer therapy." (PMID 22032647, 2011). "In addition to NOX4, NOX1-mediated enhancement of ROS generation might result in bladder cancer cells of a more aggressive phenotype." (PMID 22032647, 2011).
Cachexia (7 papers, 2021 to 2025). Severe weight loss, wasting of muscle, loss of appetite, and general debility related to a chronic disease. "SIRT1 knockout induced NF-kB signaling and enhanced NADPH oxidase 4 (NOX4) transcription in cachexia muscles caused by PC, leading to increased reactive oxygen species (ROS) levels and FOXO expression." (PMID 38725864, 2024). "In turn, the signaling axis, including SIRT1 and NOX4, may be a regulator of cellular senescence and oxidative stress, which may act as a cachexia regulator." (PMID 38334644, 2024).
kidney injury (7 papers, 2017 to 2024). Trauma to the kidney. "In conclusion, chronic pharmacological inhibition of NOX4 contributes to preserved mitochondria and kidney function in a mouse model of IR-induced kidney injury." (PMID 38671936, 2024). "In kidney injury, Nox4 needs manganese-SOD (Mn-SOD) and copper/zinc-SOD (Cu/Zn-SOD) to catalyze the dismutation of •O2− to H2O2 in the mitochondrial matrix and intermembrane space, respectively." (PMID 35624699, 2022). "This indicates that Nox4-mediated oxidative stress is involved in hyperoxaluria-induced kidney injury." (PMID 34201387, 2021). "It has been reported that kidney injury induces the expression and activation of NOX-4, which plays a major role in ROS generation leading to alterations in signaling pathways related to cellular proliferation, migration, and apoptosis." (PMID 29177025, 2017). "In this study, we demonstrated that NOX4 mediated OS and senescence in Aldo-induced kidney injury." (PMID 33757397, 2021).
preeclampsia (7 papers, 2014 to 2025). Preeclampsia is a hypertensive disorder of pregnancy that is characterized by new-onset hypertension with proteinuria presenting after 20 weeks of gestation, and depending on mild or severe forms may initially present with severe headache, visual disturbances, and hyperreflexia. "NOX4 is also involved in placental redox reactions, with upregulated levels observed in preeclampsia." (PMID 41440029, 2025). "Angiotensin has been shown to stimulate NOX4-mediated oxidative stress in podocytes, and placental NOX4 protein expression is upregulated in preeclampsia." (PMID 41416997, 2025). "NOX4 gene expression regulates the production of ROS, whose excess generation can increase the incidence of diseases such as preeclampsia and lead to placental abruption or stillbirths." (PMID 38473152, 2024). "It is suggested that enhanced ROS production in the RVLM in preeclampsia rats is highly associated with the NADPH oxidase, especially NOX4 subunit." (PMID 29085302, 2017). "In this study, we had observed a significant increase in the NADPH oxidase subunits-NOX4 protein expression in the RVLM in preeclampsia rats." (PMID 29085302, 2017). "On the other hand, four proteins (Endoglin, Nox4, Flt-1 and Calretinin) were positively correlated and two proteins (AnnexinXI and PlGF) were inversely correlated with the severity of term preeclampsia (P<0.05, R value≥0.4)." (PMID 25392996, 2014). "In this investigation, we demonstrated numerous key genes (ALB, NOX4, CDKN2A, TXNRD1, and CAV1) that are expected to act as biomarkers for ferroptosis in STB-EVs of preeclampsia." (PMID 36343018, 2022). "In this study, we identified several central genes closely related to ferroptosis in STB-EVs (ALB, NOX4, CDKN2A, TXNRD1, and CAV1) that are potential biomarkers related to ferroptosis in preeclampsia." (PMID 36343018, 2022). "On the other hand, Calretinin, HtrA, Flt-1, Nox4 and Endoglin were positively and Annexin XI and PLGF were inversely correlated with the severity of term preeclampsia." (PMID 25392996, 2014). "Renal gene expression of Hsd11b2, Sgk1, Scnn1a, Nox4, and Fn1 was not different between mice who had a normal pregnancy and mice who had a preeclampsia-like pregnancy at 5 or 10 weeks postpartum (respectively)." (PMID 40425613, 2025). "ALB, NOX4 and CAV1 are associate with the prosses of preeclampsia, and the other two genes (CDKN2A, TXNRD1) have not been linked directly to the occurrence of preeclampsia." (PMID 36343018, 2022).
thyroid tumor (7 papers, 2018 to 2026). A benign or malignant neoplasm affecting the thyroid gland. "DUOX1 and NOX4 are involved in the generation of ROS in the context of thyroid tumor development, which opens the way for further investigation into their role in the mechanisms that lead to genetic aberrations." (PMID 40620232, 2025). "More than 90% of C-PTC infiltrating tumors overexpressed NOX4 protein (score ≥ 2), suggesting a role of NOX4 in thyroid tumor aggressiveness." (PMID 37504283, 2023). "NOX4 protein expression was analyzed by immunohistochemistry staining in thyroid tumor tissues and their paired NAT." (PMID 37504283, 2023). "Importantly, all thyroid tumors (BRAFV600E) overexpressed NOX4 protein (100%: 10 C-PTC/10-C-PTC), highlighting the positive correlation between BRAFV600E mutation and NOX4 protein expression in PTC (p-value < 0.0001)." (PMID 37504283, 2023). "However, a non-negligible percentage of BRAFwt thyroid tumors (68.4%: 26/38) also exhibited a high level of NOX4 expression." (PMID 37504283, 2023).
viral infection (7 papers, 2015 to 2022). "It is interesting that the early effects on inflammation were more pronounced than at later time points suggesting that the viral infection eventually overrides the early effects of NOX4 ROS production presumably as the cytokine response gains momentum." (PMID 35601109, 2022). "We here show that MHV-3 triggers NOX-derived ROS secretion in macrophages by inducing NOX-subunits, including GP91phox, p47phox and NOX-4 expression in the very early stages of the viral infection." (PMID 26367131, 2015). "It is well known that in viral infections, NOX4 upregulation might be part of the response to the infection leading to protective apoptosis of the infected cell." (PMID 35662702, 2022). "In addition to the ROS generated by iNOS, ROS are also generated by NADPH oxidase 4 (NOX4), which is up-regulated following viral infection in the lungs." (PMID 34698139, 2021). "The opposing effects of NOX4 and endosomal NOX2 on inflammation and cytokine signalling might therefore be of significance for the exacerbated inflammation and pathogenesis resulting from influenza and other viral infections." (PMID 35601109, 2022).
atrial fibrillation (6 papers, 2018 to 2025). A disorder characterized by an electrocardiographic finding of a supraventricular arrhythmia characterized by the replacement of consistent P waves by rapid oscillations or fibrillatory waves that vary in size, shape and timing and are accompanied by an irregular ventricular response. "Pak2 was reduced and NOX4 increased in atrial appendage tissue from cardiopulmonary bypass patients with atrial fibrillation compared to patients with sinus rhythm." (PMID 40068092, 2025). "NOX4 has come into focus in the setting of cardiac disease, as NOX4 expression has been found to be elevated in HF, atrial fibrillation, and atherosclerosis." (PMID 31857574, 2019). "Activation of NOX2 and NOX4 occurs in humans with atrial fibrillation and inhibition of NOX by angiotension converting enzyme inhibitor drugs or statins has proved helpful in preventing post-operative atrial fibrillation." (PMID 29686666, 2018). "NADPH oxidase accounts for the main ROS source during atrial fibrillation, especially NOX2 and NOX4." (PMID 39775356, 2025). "Similarly, cardiac tissue from AF patients, showed a Pak2 downregulation and NOX4 upregulation implicating these changes in human atrial fibrillation." (PMID 40068092, 2025).
cerebral infarction (6 papers, 2014 to 2024). An ischemic condition of the brain, producing a persistent focal neurological deficit in the area of distribution of the cerebral arteries. "Furthermore, pharmacological inhibition of TLR4-NOX4 signalling led to reduced expression of NOX4 and a subsequent decrease in volume and area of cerebral infarction of 40%." (PMID 26785066, 2014). "Previous studies have reported that PLB had the role in inhibiting NADPH oxidase 4 (NOX4) and regulating redox signaling and protected cerebral infarction-reperfusion-induced neurogenic injury in rats through the repression of apoptosis and NF-κB activation." (PMID 33344645, 2020). "NOX1, NOX2 and NOX4 are the main brain isoforms, and mice with genetic deletion of the gp91phox catalytic unit of NOX2 exhibited reduced brain infarction after tMCAO, even if neutrophil NOX2 was rescued with a bone marrow transplant." (PMID 33192266, 2020). "Thus, we speculated that benzyl ferulate also has antioxidation action theoretically, which was confirmed by the results that benzyl ferulate attenuated brain infarction size of rats via inhibiting the expression of NOX2 and NOX4." (PMID 39524533, 2024). "In particular, iNOS is expressed in infiltrating neutrophils and endothelial cells 6–96 h after MCAO in rats and in human cerebral infarcts, adding NO fuel to the fire and synergizing oxidatively with superoxide emanating from neutrophil NOX2 and endothelial NOX4." (PMID 33192266, 2020).
cervical cancer (6 papers, 2017 to 2024). A primary or metastatic malignant neoplasm involving the cervix. "Considering the significant role of ROS in pathophysiology, regulating the entry of extracellular ROS produced by NOX4 into cells to promote pro-cancer signaling in cervical cancer has become a pressing research concern." (PMID 38230207, 2024). "Our data demonstrates that inflammatory mediator TGF-β1 stimulates cervical cancer cells to accelerate metabolism, prompting NOX4 in the cell membrane to produce large amounts of ROS, which are converted to relatively stable H2O2." (PMID 38230207, 2024). "Taken together, our results suggest that AQP3 promotes cervical cancer invasion and metastasis by regulating NOX4-derived H2O2 transport into cancer cells, thereby activating the Syk/PI3K/Akt signaling pathway." (PMID 38230207, 2024). "TGF-β1 promoted the invasion and migration of cervical cancer cells by activating NOX4 to generate ROS production." (PMID 34568577, 2021). "Geo profiles database in NCBI showed that the expression of NOX4 and p22phox are significantly elevated in cervical cancers suggesting NOX4-p22phox is activated in cervical cancer for migration and invasion." (PMID 28099519, 2017). "In this study, we utilized cervical cancer HeLa cell line and established a xenograft tumor model in nude mice, and then we investigated the role and mechanism of AQP3 in the invasion and metastasis of cervical cancer by controlling NOX4-derived H2O2 signaling." (PMID 38230207, 2024). "To uncover the molecular mechanism underlying the oncogenic effects of AQP3 in cervical cancer cells, we found by immunoprecipitation experiments that AQP3 inter-acts with NOX4 and may co-form complexes at the cell membrane." (PMID 38230207, 2024). "PLB has been reported to induce free radical species in cervical cancer cells, as well as being an inhibitor of NADPH oxidase-4, while 2-amino-1,4-naphthoquinone could induce the production of free radicals." (PMID 35453530, 2022). "In addition, we analyzed the expression NOX4 and p22phox in cervical cancers using the database since we used HeLa cervical cancer cell line." (PMID 28099519, 2017). "AQP3 interacts with NOX4 in the cell membrane, and a large amount of H2O2 flows into the cell through the open AQP3 channel, which acts as a signaling molecule to activate the Syk/PI3K/Akt pathway, promoting the invasion and metastasis of cervical cancer." (PMID 38230207, 2024). "The results indicate that NOX4-derived H2O2 transmembrane transport induced by growth factors is regulated by AQP3, and AQP3-dependent H2O2 signaling activates intracellular Syk/PI3K/Akt signaling cascades that promote the invasion and metastasis of cervical cancer." (PMID 38230207, 2024).
Cirrhosis (6 papers, 2015 to 2025). A chronic disorder of the liver in which liver tissue becomes scarred and is partially replaced by regenerative nodules and fibrotic tissue resulting in loss of liver function. "The deficiency of NOX1 or NOX4 prevents liver inflammation and fibrosis in mice and NOX1 and NOX4 protein levels are increased in human livers with cirrhosis compared with normal controls." (PMID 34571961, 2021). "Finally, NOX1 and NOX4 protein levels were increased in human livers with cirrhosis compared with normal controls." (PMID 26222337, 2015). "Indeed, the demonstration that NOX4 deficiency may promote HCC in cirrhotic livers suggests that long-term, complete inhibition of NOX4 in patients with advanced cirrhosis may carry risks." (PMID 41516036, 2025). "Furthermore, NOX1 and NOX4 are increased in patients with cirrhosis." (PMID 26222337, 2015).